IGF1R (insulin like growth factor 1 receptor)
Diseases named in the same sentence as IGF1R in open-access papers (continued):
Sharing a sentence is not in itself a finding about the gene and the disease.
cancer (continued). "DORexo contained enhanced levels of IGF-2 and IGFBP2, and we are wondering if the promotive effect of BMSCs on cancer cell growth in bone marrow is through activating IGF-1R." (PMID 36568212, 2022). "These seemingly conflicting reports can be reconciled when considering what is currently known about IGF1R function in the context of tissue development and cancer as it relates to cellular growth, proliferation, and differentiation." (PMID 35784559, 2022). "Here we detected that A549 cancer cells cultured with higher extracellular glucose concentrations have upregulated IGF1R and EGFR expression on their cell membrane." (PMID 35574343, 2022). "Insulin-like growth factor 1 receptor (IGF1R) plays an important role in cancer biology, and its nuclear localization has been described as an adverse prognostic factor in different tumors." (PMID 35574033, 2022). "Constitutive activation of the IGF1R tyrosine kinase domain is a common event in cancer cells, although the prognostic significance of IGF1R levels and activation status in clinical settings remain unsettled." (PMID 35432218, 2022). "Further, inhibition of IGF-1R sensitizes cancer cells to chemotherapy and irradiation identifying it as a promising target for molecular therapy." (PMID 35241721, 2022). "Overexpression of IGF1R has also been shown to promote a number of cancers, including breast, gastrointestinal and prostate cancer." (PMID 36335114, 2022). "In non-small cell lung cancer, IGF-1R is often overexpressed and can mediate the cancer proliferation." (PMID 36499216, 2022). "The PIK3CA gene encodes a protein kinase that mediates signaling from insulin-like growth factor receptor IGF1R to the AKT pathway, is frequently mutated in a number of cancers, and is itself the target of several chemotherapeutic agents." (PMID 35768873, 2022). "In an in vivo study, the presence of high IGF-1 levels in the primary tumor environment tended to induce cancer cells to metastasize to bone, and cancer cell lines that highly expressed IGF1R were prone to display enlarged bone mass." (PMID 35370981, 2022). "INSR and IGF-1R are frequently overexpressed in cancer cells, where they activate a variety of intracellular signaling cascades that inhibit apoptosis and promote cell cycle progression." (PMID 36295073, 2022). "The available data support that IGF1 receptor (IGF1-R) is capable of controlling cell proliferation and metastasis in cancer." (PMID 35964060, 2022). "IGF2 binding activates IGF1R and IGF2R and is associated with aberrant glucose metabolism and proteoglycan dysregulation, which is responsible for cancer development." (PMID 35391781, 2022). "We also identified IGF1R, a key tyrosine kinase receptor in regulating cancer cell survival, proliferation, and motility." (PMID 35550247, 2022). "In patient-derived cancer organoids, we observed that organoid size was positively correlated with elevated IGF1R signaling activity." (PMID 35668108, 2022). "The evidence for the importance of IGF1 signalling in cancers was obtained in a study showing that IGF-1 binding to IGF-1R and the downregulation of this receptor are similarly efficient in the inhibition of RCC cell lines’ growth." (PMID 35328822, 2022). "The increased Hsp90 expression along with its client proteins, EGFR, IGF-1R, and Src, promotes autophagy in cancer cells and confers drug resistance." (PMID 36348391, 2022). "It implied that DORexo BMSCs increased the survival and metastasis of cancer cells through IGF-1R activation." (PMID 36568212, 2022). "A prominent group of cancer-type-specific differential dependencies are six genes in the IGF1R and PI3K pathways across several cancer types." (PMID 35382456, 2022). "PKM2 facilitates HSP90-independent stability of IGF-1R precursor protein as well as enhances growth of cancer cells in a hypoxic environment." (PMID 35502178, 2022).
cancer (continued). "The mechanistic target of rapamycin (mTOR) also depends on IGF1R signaling in cancer cells and directly leads to protein biosynthesis and anabolic metabolism." (PMID 35574343, 2022). "Overexpression of miR-320a was reported to significantly downregulate the protein expression of IGF1R in cancer." (PMID 35012004, 2022). "Currently, several strategies have been developed to inhibit IGFs/IGF-1R signaling in cancer therapy." (PMID 36233084, 2022). "Most experimental evidence gathered in recent years on the role of nuclear InsR/IGF1R was generated using cancer cell lines as well as freshly obtained tumors or archival specimens." (PMID 33918477, 2021). "Cancer cells devoid of membranous IGF1R immunostaining (m-IGF1R 0) were observed in 158 (98.8%) cases." (PMID 34638472, 2021). "Evidence suggests that thyroid cancer cells and precursors of the cancer cells are responsive to the activity of insulin and IGFs, and frequently overexpress IR and IGF-1R during the early stage in thyroid carcinogenesis." (PMID 33669363, 2021). "As a result, the activation of IGF-1/IGF-1R is further inhibited, which indirectly leads to an antiproliferative effect in cancer cells." (PMID 34208601, 2021). "They identified an increase in autocrine IGF1/AKT signaling in dormant cancer cells, and showed that pharmacological inhibition of IGF-1R reduces residual tumor and cancer recurrence." (PMID 35008235, 2021). "To conclude, our comprehensive pan-cancer analysis has characterized IGF-1/IGF-1R expression in different cancer cell lines and tissues." (PMID 34804946, 2021). "Our study showed that IGF-1 and IGF-1R harbor distinct prognostic values among different cancer types." (PMID 34804946, 2021). "Currently, IGF-1R has been recognized as a major determinant of cancers, while its biological roles and exact tumorigenesis mechanisms remain elusive." (PMID 34638601, 2021). "In the MSK-IMPACT clinical sequencing cohort of over 10,000 cancer patients 2.4% had a genetic alteration in IGF-1R." (PMID 33816477, 2021). "Both, IGF2 and its receptor IGF1R constitute desirable therapeutic targets; mainly due to these evidences showing that targeting either IGF2 or its receptor IGF1R, blocks cancer progression and displays significant antitumor activity." (PMID 35095996, 2021). "Interaction of insulin-like growth factor-1 receptor (IGF1R) with Ranbp2 is essential for IGF1R sumoylation that plays a crucial role in cancer cell progression." (PMID 34635181, 2021). "IGF-1 treatment induced the expression of NANOG and OCT4 and sphere formation in HepG2.2.15, Hep3B, and PLC5 cell lines, and inhibition of IGF-1R by shIGF-1R suppressed cancer stemness properties in these cell lines." (PMID 33669204, 2021). "It is well established that ionizing radiation activates tyrosine kinase receptors involved in DNA damage response, including the IGF1R, as in fact targeting the IGF1R enhances radiosensitivity of different cancer cell lines." (PMID 33673232, 2021). "YAP is a co-transcription factor that induces transcription of a variety of genes related to cell proliferation (E2F and Cyr61), cell survival (survivin and Bcl2), cancer stemness markers (Oct4, Nanog, and IGF-1R), and EMT markers." (PMID 34359714, 2021). "As tumors grow, a portion of cancer cells acquire stemness properties due to induction of critical pluripotent transcription factors by IGF/IGF-1R signaling, followed by functional alterations in these cells." (PMID 33669204, 2021). "It has been reported that inflammatory cytokines work together with IGF/IGF-1R signaling in regulating cancer stem cell populations." (PMID 33669204, 2021). "Correlation occurred more frequently between the presence of this IGF-1R polymorphism, serum IGF-1 concentration and more advanced CRC than cancer in the early stages." (PMID 34208601, 2021). "IGF-1R signaling has shown crucial roles in the development and progression of several types of cancer and resistance to various anticancer therapies." (PMID 33408789, 2021).
cancer (continued). "In consideration of ACLY and IGF1R as promising therapeutic targets, we further designed a pharmacological strategy to verify their crucial anti-cancer roles." (PMID 34075028, 2021). "Evidence shows that targeting either IGF2 or its receptor IGF1R blocks cancer progression and displays significant antitumor activity." (PMID 33407516, 2021). "Being able to discern differential downstream signaling, we can explore improved anti-IGF1R cancer therapies by eliminating the emergence of compensation mechanisms without disrupting InsR signaling." (PMID 34191793, 2021). "The identification of InsR and IGF1R in the nucleus of normal and cancer cells has generated a significant level of interest in recent years." (PMID 33918477, 2021). "Our findings reveal a novel mechanism for regulating IGF-1R protein expression, thus suggesting PKM2 as a potential therapeutic target in cancers associated with aberrant IGF signaling." (PMID 34359752, 2021). "The cross examination of the IR’s expression profile in PDAC lead to intriguing results and shed a new light on the IR-/IGF1-R-axis in cancer." (PMID 34638472, 2021). "IGF1R overexpression has been found in many human cancers, including OS, and the application of IGF1R in treating OS has also been explored." (PMID 34503279, 2021). "It was found that most cancer types showed a higher IGF-1/IGF-1R alteration frequency and the expression of IGF-1 and IGF-1R served as the prognostic factor in some cancer types, including BLCA and LAML upon both Cox and KM survival analyses." (PMID 34804946, 2021). "IGF1R itself has important functions in fetal and prenatal growth and in cancer proliferation, by promoting the immortalization of transformed cells through binding to two insulin-like growth factors, IGF-1 and IGF-21–3." (PMID 33608571, 2021). "Over-expressed IGF1R promotes DNA repair in primary human lung fibroblasts, several human cancer cells and irradiated salivary glands." (PMID 34178997, 2021). "IGF1R regulates “Proteoglycans in cancer,” “PI3K-Akt signaling pathway,” “Pathways in cancer,” “Ras signaling pathway,” “Rap1 signaling pathway,” and “Transcriptional misregulation in cancer”." (PMID 34557357, 2021). "Recently, hypoxia has been shown to activate insulin-like growth factor 1 receptor (IGF1R), which can lead to the generation of primitive cancer stem cells and EMT." (PMID 34572868, 2021). "The association between IGFBP6 and cancer appears to be more obvious, as a large number of studies on the role of the IGF/IGF1R signaling pathway in oncogenesis have been carried out to date." (PMID 34149804, 2021). "It has been reported that IGF1R expression levels correlate with progression of cancer and metastatic phenotypes." (PMID 34071893, 2021). "Rationale: The type I insulin-like growth factor receptor (IGF-1R) signaling pathway plays key roles in the development and progression of numerous types of human cancers, and Src and AXL have been found to confer resistance to anti-IGF-1R therapies." (PMID 33408789, 2021). "IGF1, a paracrine factor released by radiotherapy-treated CAFs, induces IGF1R/InsR phosphorylation in cancer cells, leading to Akt activation." (PMID 34503536, 2021). "IGF-1R is overexpressed in a variety of cancers including colon, pancreatic, prostate, lung, and breast cancers." (PMID 34867402, 2021). "mTOR signaling factors downstream of IGF1R play key roles in the regulation of cancer cell metabolism, lipid and protein synthesis and they are responsible for several metabolic adaptations." (PMID 34178997, 2021). "It was also demonstrated that patients with HBV-HCC have higher recurrence rates and higher expression levels of IGF-1R and cancer stemness markers." (PMID 33669204, 2021). "It has been shown that upregulation of IGF/IGF-1R signaling results in an increase of cancer stemness properties in HCC." (PMID 33669204, 2021). "This remodulation of IGF/IGF-1R signaling can induce Nanog expression and contribute to cancer stemness." (PMID 33669204, 2021).
cancer (continued). "Existing research shows that IGF1R is abnormally expressed in many cancers, which is closely related to the development of malignant tumors." (PMID 34093664, 2021). "A direct role for IGF/IGF-1R signaling in regulating the stem cell niche and cancer stem cell niche has been reported." (PMID 33669204, 2021). "The impact of high IGF-1 and IGF-1R on prognosis and immune infiltrates differs across cancer types." (PMID 34804946, 2021). "The regulation of NANOG and OCT4 in HCC cancer stem cells by IGF/IGF-1R signaling was elucidated in HCC cell lines." (PMID 33669204, 2021). "We previously illustrated that high expression of IGF-1R correlates with expression of cancer stemness markers (OCT4 and NANOG) and early recurrence and with sorafenib resistance properties in HCC." (PMID 34359714, 2021). "On the other hand, studies have proved that anti-IGF-1R monoclonal antibody has potential therapeutic value in diverse cancers." (PMID 34804946, 2021). "CAFs have been reported to regulate cancer stemness by inducing a de-differentiation program mediated by Nanog, through the release of paracrine factors and activation of insulin-like growth factor 1 receptor (IGF1R) signalling." (PMID 34572431, 2021). "IGF1 and IGF2 are the major ligands in this system, and potent mitogens and anti-apoptotic peptides that affect cancer cell proliferation and survival via activation of the insulin-like growth factor-1 receptor (IGF-1R) signaling." (PMID 33976188, 2021). "The reported negative impact of IGF1R expression on PDAC patient survival and the synergism between the IGF1R and IR described for other cancer entities gives reason to suspect that the IR plays a role in PDAC biology and outcome." (PMID 34638472, 2021). "Taken together, these findings suggest that HBV induces cancer stemness properties through the activation of IGF/IGF-1R signaling." (PMID 33669204, 2021). "cCC-IR, mCC-IR, VIR, m-IGF1R and c-IGF1R were found to be heterogeneously expressed within the cancer site." (PMID 34638472, 2021). "CAF-secreted IGF2 provides a feedback pathway with IR/IGF1R to induce the resistance of cancer cells to erlotinib, a tyrosine kinase inhibitor (TKI)." (PMID 33732706, 2021). "Neuropilin-1 (NRP1, BDCA-4) induces a c-Jun N-terminal kinase (JNK)-dependent signaling cascade that leads to the upregulation of EGFR or IGF1R, thereby promoting cancer cell growth." (PMID 33732282, 2021). "The correlation between the expression of IGF-1/IGF-1R and the immune infiltration levels across diverse cancer types is derived from TIMER." (PMID 34804946, 2021). "Malignant progression is often associated with upregulated insulin-like growth factor receptor (IGF-1R) expression and/or signaling as documented in diverse cancer types, including TNBC." (PMID 33916323, 2021). "Noticeably, IGF/IGF-1R signaling was identified as the molecular mechanism involved in regulating the cancer stemness characteristics of these cells." (PMID 33669204, 2021). "In the next paragraphs, we will discuss the crosstalk between IGF1R/IR and some novel partners and the role that these interactions play in regulating cancer initiation and progression." (PMID 33673232, 2021). "Based on these insights, diminishing cancer stemness can be further explored through targeting both IGF/IGF-1R signaling molecules and epigenetic modulators." (PMID 33669204, 2021). "IGF/IGF-1R signaling has been reported to induce the expression of cancer stemness-related transcription factors, including IGF-1R, NANOG, OCT4, NFκB, STATs, SOX2, and YAP." (PMID 33669204, 2021). "Fractionated radiation induces an increase in IGF1 secretion level and gradually up-regulates IGF1R expression in cancer stem cells (GSCs)." (PMID 34178997, 2021). "The IGF1R was identified as a promising therapeutic target for intervention as it is overexpressed in various cancers and is involved in pro-mitotic and pro-survival signaling." (PMID 34031486, 2021).
cancer (continued). "The IGF1R is a known resistance mechanism involved in several treatment approaches for a variety of cancers including HNSCC47–50." (PMID 34031486, 2021). "Of these, IGF-1R is overexpressed in cancer cells, has a crucial role in tissue development, and is activated by the hormone IGF-1." (PMID 34299089, 2021). "Increased levels of Src expression and kinase activity have been reported in various human cancers 21, 22 and often induce resistance to various molecularly targeted anticancer drugs, including IGF-1R inhibitor-based therapies." (PMID 33408789, 2021). "Even preclinical studies show that targeting IGF1R inhibits cancer cell progression, and results of clinical trials evaluating anti-IGF1R strategies as cancer treatment have been disappointing." (PMID 33429867, 2021). "Results suggest a role for inflammation in promoting cancer stemness in HCC through IGF/IGF-1R signaling." (PMID 33669204, 2021). "Previous studies revealed that IGF-1R was critically involved in PC pathophysiology, promoting cancer cell survival and therapeutic resistance." (PMID 34899908, 2021). "The first anti-IGF1R mAb αIR3 showed efficacy in preclinical studies by inhibiting cancer cells’ growth both in vitro and in vivo." (PMID 34440844, 2021). "There are numerous reports that have characterized the role of the IR/IGF-1R signaling pathway in the tumorigenesis and metastasis of various cancers." (PMID 33603563, 2021). "We believe that by determining ways to suppress IGF1R signaling alone, we can find more effective ways of preventing cancer and inhibiting its progression." (PMID 34191793, 2021). "On the other hand, high expression of IGF-1R served as a significant prognostic factor in such cancer types including KIRC and LAML; whereas in BLCA, LIHC, and LUAD, low expression of IGF-1R served as a favorable prognostic factor." (PMID 34804946, 2021). "Despite this, it has been shown that HER-2 overexpressing cancers treated with PI3K inhibitors developed AKT-mediated activation of other tyrosine kinase growth factors such as IGF1-R, Ins-R, and HER3 treatment." (PMID 33829018, 2021). "IGF-1R expression was correlated with at least one MMR genes in almost all of the 33 cancer types except for BRCA, STAD, and UCS." (PMID 34804946, 2021). "In recent years, novel proteins affecting the activity of the IGF1R and IR in cancer have been identified." (PMID 33673232, 2021). "IGF-1R activity and expression are frequently increased in malignant tumours showing it to certainly play a role in the progression of tumourigenesis." (PMID 33816477, 2021). "According to our results, IGF-1 and IGF-1R can serve as a valuable prognostic biomarker in some cancer types." (PMID 34804946, 2021). "In certain cancers, IGF1R signaling contributes to oncogene-induced cancer transformation, thus suggesting that IGF1R signaling pathway is an attractive therapeutic target for cancer chemotherapy." (PMID 34071893, 2021). "These mutations include focal amplification of IGF1R and IGF1, and frameshift indels in the recessive cancer genes IGF2R and IGFBP5." (PMID 33673232, 2021). "More importantly, the IGF-1/IGF-1R system mediates stimulatory effects in cancer cells via different routes such as the phosphatidylinositol-3kinasw(PI3K)/Akt1, mTOR, and MAPK." (PMID 35010954, 2021). "Implication of IGF1R in cancer has prompted the development of anti-cancer strategies using neutralizing antibodies and small-molecule inhibitors of the RTK4." (PMID 33608571, 2021). "In this study, we analyzed the impact of IGF-1 and IGF-1R on the abundance of six immune infiltrates in cancers that harbor prognostic value, which are B cells, CD4+ cells, CD8+ cells, dendritic cells, macrophages, and neutrophils." (PMID 34804946, 2021). "IGF-1R, which promotes cell growth and survival, is also commonly upregulated in cancers such as breast, colorectal and prostate cancer." (PMID 33053840, 2020).